MUC16 (mucin 16, cell surface associated)
Diseases named in the same sentence as MUC16 in open-access papers (continued):
Sharing a sentence is not in itself a finding about the gene and the disease.
neuroblastoma (2 papers, 2013 to 2024). Neuroblastoma (NB) is the most common solid, extracranial childhood tumor. "The frequencies of MUC4, MUC16, and KMT2C have also been substantially high in previous studies, implying their roles in neuroblastoma development." (PMID 39338204, 2024). "MUC16 is a member of a large family of mucin coding genes and NBPF10 is from the neuroblastoma breakpoint family, which consists of 22 genes and pseudogenes that arose by gene duplication." (PMID 23940540, 2013). "Moreover, the frequency of MUC4 and MUC16 mutations in our study was considerably higher than that reported in a previous study on MYCN non-amplified neuroblastoma (70% vs. 26% for MUC4 and 38% vs. 14% for MUC16)." (PMID 39338204, 2024).
neuroendocrine tumors (2 papers, 2020 to 2023). "Chromogranin A (CgA) is a biomarker for neuroendocrine tumors and biomarkers MUC16 (CA-125) and HE4 for ovarian cancer." (PMID 33302373, 2020).
Ovarian cyst (2 papers, 2025 to 2026). The presence of one or more cysts of the ovary. "CA19-9 antigens were immobilized from ascites fluids, ovarian cyst fluids or serum samples using monoclonal antibody C192 followed by probing of carrier proteins using anti-MUC16, anti-MUC1 and, anti STn antibodies and seven lectins, all separately coated on nanoparticles." (PMID 39863644, 2025).
periodontal disease (2 papers, 2023 to 2025). "TMB analysis revealed that low TMB correlated with tobacco-related SBS4 and SBS5, whereas high TMB was associated with periodontal disease and mutations in KMT2C, MUC16, and CASP8, as well as the ID-19 signature." (PMID 41154345, 2025). "In this study, a positive correlation between M-CSF and CD125/MUC16 was observed in elderly individuals with periodontal disease and HIV-positive patients." (PMID 37762764, 2023). "The SBS 5 signature was associated with the presence of periodontal disease (n = 8, 33.3% vs. n = 2, 8.3%; p = 0.004), higher recurrence risk (OR = 12.3, 95% CI: 1.3–109; p = 0.016), lower tumor burden (OR = 3.5, 95% CI: 1–11.9, p = 0.035), and absence of the MUC16 mutation (p = 0.015)." (PMID 41154345, 2025). "In our cohort, SBS5 was correlated with periodontal disease, lower TMB, higher recurrence risk, and absence of MUC16 mutations." (PMID 41154345, 2025).
psoriasis (2 papers, 2009 to 2025). An autoimmune condition characterized by red, well-delineated plaques with silvery scales that are usually on the extensor surfaces and scalp. "In order to clarify the potential role of MUC16 in psoriasis and to identify the causal variant(s) at this locus, further functional studies are necessary." (PMID 19525279, 2009). "Among the top 10 downregulated and top 10 upregulated DEG, we identified several key genes related to psoriasis, including Krt25, Krt8, Muc16, Slc5a7, Reg3b." (PMID 39665264, 2025). "Further analysis of epidermis barrier function revealed that Muc16, which encodes an epithelial protein marked as compromised barrier function in psoriasis, was significantly downregulated following nor@MSC‐EVs treatment compared to PBS." (PMID 39665264, 2025). "Interestingly, an adjacent gene, MUC16, coding for a large glycosylated protein expressed in epithelia and of unknown function, could be shown to be also expressed in tissues relevant for pathogenesis of psoriasis such as skin and thymus." (PMID 19525279, 2009).
sarcoma (2 papers, 2020 to 2022). A usually aggressive malignant neoplasm of the soft tissue or bone.
serous ovarian tumor (2 papers, 2020 to 2025). "In our 2024 publication presenting the revised molecular model of MUC16, we reported the observation of possible splice variants in MUC16 mRNA from a high-grade serous ovarian tumor." (PMID 40361385, 2025). "Tn/STn-MUC16 and MUC1 glycoforms are differently expressed in borderline and malignant serous ovarian tumors from benign lesions, suggesting this glycoform signature as a promising tumor-associated biomarker." (PMID 33019700, 2020).
sexually transmitted infection (2 papers, 2025). "Including healthy controls with no history of tobacco or alcohol use, penile lesions, or venereal disease allowed for the identification of shared mutations (PABPC1, MUC16, and KAT6B) between groups." (PMID 40486961, 2025).
skin cancer (2 papers, 2018 to 2024).
viral hepatitis (2 papers, 2022). An acute or chronic inflammation of the liver parenchyma caused by viruses. "In MUC16, MMs were associated with viral hepatitis, higher tumor marker levels and vascular invasion." (PMID 36199046, 2022).
anaplastic astrocytoma (1 paper, 2015). "In a dataset of anaplastic astrocytomas, mutations in two of these four genes (PKHD1 and MUC16) were identified and in a set of GBMs, mutations in three genes (MUC16, F5 and PKHD1) were identified." (PMID 26699864, 2015).
atopic dermatitis (1 paper, 2019). "For this reason, it is important to evaluate the presence or absence of corneal epithelial disorders before initiation of eyewash use, and we will investigate the mucins other than MUC5AC and MUC16 and the efficacy of eyewash use in patients with atopic dermatitis in the future." (PMID 31614909, 2019).
chondrosarcoma (1 paper, 2022). A malignant cartilaginous matrix-producing mesenchymal neoplasm arising from the bone and soft tissue. "Also, the fusion of HEY1-NCOA2 and mutations of MUC16 were detected in all mesenchymal chondrosarcomas." (PMID 35756627, 2022).
CNS DLBCL (1 paper, 2022). "Some highly mutated genes in primary CNS DLBCL, such as MUC16, ODZ4 and SLIT2 reported in the previous studies were not covered in our present NGS panel." (PMID 35223507, 2022).
CNS leukemia (1 paper, 2022). "Of the 7 children with CNS leukemia, 1 was JAK2+, 1 was FLT3+, and 1 was MUC16+." (PMID 35733807, 2022).
colorectal adenocarcinoma (1 paper, 2022). The most common type of colorectal carcinoma. "Comparative studies using MUC16 and other tumor markers, such as carcinoembryonic antigen, have been conducted on colorectal adenocarcinomas." (PMID 36051359, 2022).
esophageal squamous cell carcinoma (1 paper, 2025). Esophageal squamous cell carcinoma (ESCC) is a type of esophageal carcinoma (EC) that can affect any part of the esophagus, but is usually located in the upper or middle third. "Cancer cells expose cancer antigens on their surface, such as CA125 (MUC16) (cancer antigen 125), HE4 (human epididymis protein 4), WT1 (Wilms’ tumor 1), NY-ESO-1 (New York esophageal squamous cell carcinoma 1), or mesothelin, which T lymphocytes can recognize." (PMID 40362280, 2025).
giant cell tumor (1 paper, 2011). A benign, intermediate, or malignant tumor that arises from the bone or soft tissue. "5/8 (62.5%) of the moderate-poorly differentiated, 1/1 (100%) of well differentiated, 1/1 giant cell tumor and 1/1 of mucinous cystic adenocarcinoma expressed MUC16." (PMID 22066010, 2011).
hepatitis C (1 paper, 2022). "MMs in MUC16 were associated with hepatitis C (P < 0.001), increased PIVKAII levels (P = 0.032) and macro vascular invasion (P = 0.041)." (PMID 36199046, 2022).
invasive carcinoma (1 paper, 2011). A carcinoma that is not confined to the epithelium, and has spread to the surrounding stroma. "Like in invasive carcinoma, MUC16 predominantly localized to the cell membrane of the dysplastic cells." (PMID 22066010, 2011).
kidney cancer (1 paper, 2018). Primary or metastatic malignant neoplasm involving the kidney. "The high mutation frequency of MUC16 gene was largely due to its long sequence in some cancers such as breast, liver, kidney cancer." (PMID 29552305, 2018).
liver diseases (1 paper, 2019). "MUC16 (CA125)—the largest glycoprotein (3–5 million Da) in the Mucins family, has been identified as a prominent cancer biomarker in vivo, especially for epithelial ovarian cancers, with immunohistochemical (IHC) expression also reported in patients with liver diseases." (PMID 30875782, 2019).
liver failure (1 paper, 2021). A liver disease characterized by the liver losing or has lost all of its function. "Several elevations signified an emergence of liver failure in the urine level of CCL3, KLRD1, MUC-16, KIRLD1, TWEAK, VEGF r2." (PMID 34608231, 2021).
lung disorder (1 paper, 2019). A disease involving the lung. "Another notable result was the presence in the list of various mucin-encoding genes (MUC5B, MUC12, and MUC16), which are commonly observed mutated in many cancers and have been previously linked to colorectal, ovarian and hepatological cancers, as well as to severe fibrotic lung disorders." (PMID 31156702, 2019).
malignant rhabdoid tumor (1 paper, 2022). "MUC16, OPN, AFP, and MSLN gene expression were highly expressed in all malignant rhabdoid tumor cell lines (CHLA-02, CHLA-05, and G401)." (PMID 35954348, 2022). "AFP, MSLN, MUC16, OPN, and MT1-MMP/MMP14 may serve as biomarkers for human malignant rhabdoid tumor detection and therapeutic targets." (PMID 35954348, 2022).
mesenchymal chondrosarcoma (1 paper, 2022). A morphologic variant of chondrosarcoma arising from bone and soft tissue. "Although there are only two cases, considering the rarity of mesenchymal chondrosarcoma, the identification of the MUC16 mutation indicates the potential opportunity of mesenchymal chondrosarcoma patients to benefit from immunotherapy." (PMID 35756627, 2022). "Meanwhile, we found that the mutations of MUC16 may be a potential biomarker for the diagnosis of mesenchymal chondrosarcomas." (PMID 35756627, 2022).
mucinous adenocarcinoma of the appendix (1 paper, 2023). Mucinous adenocarcinoma of the appendix is a very rare, slow growing, well-differentiated epithelial neoplasm of the appendix characterized by abundant mucin production. "Furthermore, MUC16 is expressed in mucinous adenocarcinomas of the appendix, showing cytosolic expression and being related to lymph node metastasis since, in appendiceal carcinomas, its expression seems to be lowered." (PMID 37509254, 2023).
mucinous ovarian cancer (1 paper, 2015). An invasive malignant neoplasm that arises from the ovary and is characterized by the presence of malignant epithelial cells that contain intracytoplasmic mucin and may resemble the epithelial cells of the endocervix or gastrointestinal tract. "Two biopsies from two different mucinous ovarian carcinomas were positive for both MUC5AC and MUC16." (PMID 26075384, 2015).
mucoepidermoid carcinoma (1 paper, 2022). A carcinoma morphologically characterized the presence of cuboidal mucous cells, goblet-like mucous cells, squamoid cells, cystic changes, and a fibrotic stromal formation. "The results show that MUC1 is intensely expressed in salivary duct carcinoma, which is known for its aggressive growth and low survival rates while MUC16 shows the highest intensity in mucoepidermoid carcinoma." (PMID 35389164, 2022).
nasopharyngeal carcinoma (1 paper, 2024). A carcinoma arising from the nasopharyngeal epithelium. "As a transcription factor, ELF3 promoted mucin-16 (MUC16) expression by binding to its promoter, leading to the glycolysis-mediated immune escape of nasopharyngeal carcinoma (NPC) cells." (PMID 39219440, 2024).
NK cell leukemia (1 paper, 2010). "The NK cell leukemia cell line (NKL), which does not express KIRs but are positive for DNAM-1 and NKG2D, also conjugated and lysed MUC16-knockdown cells more efficiently than MUC16 expressing controls." (PMID 20089172, 2010).
ovarian adenocarcinoma (1 paper, 2018). An adenocarcinoma that arises from the ovary. "MUC16 and MUC20 relative expression is increased in ovarian adenocarcinoma (GSE14407, p < 0.01 and p < 0.05 respectively)." (PMID 30236127, 2018).
papillary thyroid cancer (1 paper, 2022). "Finally, we investigated the expression levels of the common mutated genes (JMJD1C, MUC16, PDZD2, RYR1, and SLA) in papillary thyroid cancer cell lines (K1, TPC-1 and BCPAP) compared to an immortalized normal thyroid epithelial cell line (Nthy-ori 3-1) by qRT-PCR." (PMID 35996174, 2022).
prostate adenocarcinoma (1 paper, 2023). "Although the exact roles of these genes in NEPC development remain to be elucidated, some of them (i.e., TTN, MUC16, and KMT2D) are reportedly associated with disease progression and treatment resistance in prostate adenocarcinoma and other types of cancers." (PMID 37025467, 2023).
respiratory failure (1 paper, 2021). The significant impairment of gas exchange within the lungs resulting in hypoxia, hypercarbia, or both, to the extent that organ tissue perfusion is severely compromised. "Respiratory failure was signified by depression of EGF, GZMA, LAP, IL-4, and IL-7, and increased expression of MUC-16, ARG-1, and LAMP-3." (PMID 34177897, 2021).
salivary gland carcinoma (1 paper, 2022). A carcinoma that arises from the major or minor salivary glands. "The current study aimed to determine the expression rate of Mucin-1 (MUC1), Mucin-16 (MUC16), and Mucin-5AC (MUC5AC) in salivary gland carcinomas (SGC) using immunohistochemistry." (PMID 35389164, 2022).
schizophrenia (1 paper, 2020). A major psychotic disorder characterized by abnormalities in the perception or expression of reality. "Although some rare alleles in MUC16 were reported in association to schizophrenia, none of the 62 rare alleles in this bin were reported before." (PMID 32415273, 2020).
small intestinal cancer (1 paper, 2014). "Aberrant expression of MUC3, MUC4, MUC5AC and MUC6 is found in pancreatic intraepithelial neoplasia, and MUC16 and MUC17 are expressed in pancreatobiliary and small intestinal cancers and have high prognostic value." (PMID 25551773, 2014). "We also previously examined mucin expression in small intestinal carcinoma, and found positive expression rates of MUC1, 51.7%; MUC2, 26.7%; MUC3, 55.0%; MUC4, 51.7%; MUC5AC, 33.3%; MUC6, 10.0%; and MUC16, 8.3% (MUC17 expression was not examined)." (PMID 25551773, 2014).
somatotropinoma (1 paper, 2020). "Our data indicated that three genes having pronounced effects on tumorigenesis were strongly downregulated by SSA/DA in somatotropinoma tissues (MUC16, MACC1, and GRHL2) and confirmed these findings in functional GH3 cell experiments." (PMID 33680922, 2020).
staphylococcal infection (1 paper, 2023). An infection caused by Staphylococcus. "A previous report presented an increase in the adherence of S. aureus after MUC16 knockdown and indicated the protective responses of MUC16 to staphylococcal infection." (PMID 37762764, 2023).
tear (1 paper, 2023). "This is because in ADDE, inflammatory mediators are likely to be accumulated in tears as a result of tear deficiency-associated delayed tear clearance, which may cause a shedding of MUC16 that leads to decreased wettability due to the resultant dysfunction of MUC16." (PMID 36673051, 2023).
thyroid tumor (1 paper, 2022). A benign or malignant neoplasm affecting the thyroid gland. "We aimed to evaluate the common mutated genes (JMJD1C, MALAT1, MUC16, PDZD2, PKHD1, RYR1, SLA and TTN) between thyroid tumor and normal samples." (PMID 35996174, 2022).
tumor (625 papers, 1990 to 2026). "CA-125, also known as MUC16, is a protein encoded by the MUC16 gene, has been a widely adopted tumor marker for ovarian cancer over the past 30 years, and has been employed to diagnose OC, as well as to measure its prognosis." (PMID 40277517, 2025). "Compared with MUC16 wild‐type tumors, tumors with MUC16 mutations showed a higher tumor mutation load and more abundant neoantigens, indicating increased tumor immunogenicity." (PMID 40022576, 2025). "In OSCC, dysregulated MUC16 expression has been linked to tumor progression, epithelial–mesenchymal transition, and immune evasion." (PMID 40422614, 2025). "It is shown that ovarian cancer ascites is abundant in albumin, complement, coagulation factors and tumour-associated proteins like CA125/MUC16, by proteomic profiling, forming a complex biochemical environment for nanoparticle absorption." (PMID 41514600, 2025). "CSMD3 and MUC16 mutations are highly correlated with increased tumor mutation burden (TMB) and poor clinical prognosis." (PMID 41419193, 2025). "In contrast, MUC16 is predominantly associated with promoting cancer cell survival and metastasis by engaging oncogenic pathways that drive tumor progression and increase chemoresistance." (PMID 39935429, 2025). "For the MUC16 SNP rs7245949 a study of the association with tumor mutation burden has shown it is associated with lower expression in markers of T-cell responses." (PMID 38172662, 2024). "In cancer, MUC16 overexpression is thought to result from altered gene responsiveness to factors in the tumour microenvironment and has been linked to attenuated cellular apoptosis, chemotherapy resistance, tumor growth, and metastasis." (PMID 38961436, 2024). "TTN and MUC16 also showed a higher mutation frequency in colon cancer patients with high tumor immune microenvironment (TIM), which also represented a higher TMB." (PMID 38758220, 2024). "The MUC16 gene has the second longest exon in the genome (chromosome 19p13, 84 exons), and is associated with increased tumor mutational burden." (PMID 39240165, 2024). "MUC16 is implicated in various tumor signaling pathways, including those in ovarian, breast, cervical, pancreatic, and colorectal cancers." (PMID 39493752, 2024). "A study involving 10195 patients across 30 solid tumors in the TCGA database showed that MUC16 mutations resulted in higher abundance of immune cells in the tumor microenvironment and increased expression of multiple inhibitory checkpoints." (PMID 39749343, 2024). "Many patients with MUC16 mutations carry a large number of passenger mutations, resulting in a higher mutation burden, an enhanced anti-tumor immune response, and a favorable prognosis in the tumor microenvironment." (PMID 38758220, 2024). "Among the oncogenes, MUC16 (mutated in 18.9% of tumours), PIK3CA (12.4%), and KRAS (11.1%) were the most frequently mutated across the profiled samples." (PMID 37550388, 2023). "As for MUC16, is one of the most commonly mutated gene in many human tumors, which is linked with enhanced growth and metastasis capacity of tumor cells." (PMID 37197421, 2023). "MUC16 mutation is related to higher tumor mutational burden (TMB) and better overall survival (OS) in gastric adenocarcinoma cases." (PMID 37341998, 2023). "The tumor subtyping studies associate MUC16 expression withbasal/squamous subtypes that are predisposed to higher stromal involvement." (PMID 36816942, 2023). "Recently, it is reported that patients with MUC16 mutations have a higher tumor mutation load and neoantigen load, and are more responsive to immunotherapy." (PMID 37814942, 2023). "Mutations in large genes (Titan, MUC16), known to be primarily associated with tumor mutational burden, were excluded from analysis." (PMID 37523561, 2023). "We expect future studies to address if the decreased myofibroblast polarization in MUC16 deficient tumors results from reshaped tumor-stromal dialogue and impaired MMT process." (PMID 36816942, 2023).